FCGR1A (Fc gamma receptor Ia)
Description:
High affinity receptor for the Fc region of immunoglobulins gamma. Functions in both innate and adaptive immune responses. Mediates IgG effector functions on monocytes triggering antibody-dependent cellular cytotoxicity (ADCC) of virus-infected cells.
Synonyms: FcRI; FcgammaRIa; CD64; FCG1; FCGR1; IGFR1; CD64A; FcgammaRI
Tractability: Small molecule: a structure with a bound ligand is known. Antibody: a drug acting on it is in phase 2 or 3 trials; UniProt places it where antibodies can reach, with high confidence; its Gene Ontology location is reachable by antibodies, with high confidence; UniProt predicts a signal peptide or a membrane-spanning region. PROTAC: a small molecule that binds it is known.
Target class: Membrane receptor
Gene: Protein-coding gene on chromosome 1 (149,782,650 to 149,792,526, forward strand). Ensembl gene ENSG00000150337.
Subcellular location: Cell membrane
Subcellular location (Human Protein Atlas): Vesicles; Golgi apparatus; Plasma membrane
Pathways (Reactome):
Immune System: Cross-presentation of soluble exogenous antigens (endosomes); FCGR activation; Immunoregulatory interactions between a Lymphoid and a non-Lymphoid cell; Interferon gamma signaling; Regulation of actin dynamics for phagocytic cup formation; Role of phospholipids in phagocytosis
Disease: FCGR3A-mediated IL10 synthesis
Gene Ontology:
Molecular function: high-affinity IgG receptor activity; protein binding; IgG binding; IgG receptor activity
Biological process: antibody-dependent cellular cytotoxicity; Fc-gamma receptor signaling pathway; cell surface receptor signaling pathway; immune response; phagocytosis, engulfment; positive regulation of phagocytosis; positive regulation of tumor necrosis factor production; signal transduction
Cellular component: plasma membrane; clathrin-coated endocytic vesicle membrane; early endosome membrane; external side of plasma membrane
Genetic constraint (gnomAD): Loss-of-function variants: 14 observed, 29.28 expected, observed/expected ratio (o/e) 0.48, 90% interval 0.31 to 0.75. The synonymous counts are far from expectation, so gnomAD's model fits this gene poorly and the ratio says little. Missense variants: 225 observed, 389.55 expected, observed/expected ratio (o/e) 0.58, 90% interval 0.52 to 0.64. Synonymous variants: 90 observed, 145.79 expected, observed/expected ratio (o/e) 0.62, 90% interval 0.52 to 0.74.
Homologues: Orthologues: chimpanzee FCGR1A (99% identical), macaque FCGR1A (90% identical), dog FCGR1A (73% identical), pig FCGR1A (69% identical), mouse Fcgr1 (66% identical), rat Fcgr1a (61% identical). Paralogues in human: FCRLB (33% identical), FCRL3 (31% identical), FCRL5 (30% identical), FCRL4 (29% identical), FCGR2B (27% identical), FCRLA (27% identical), FCGR2A (25% identical), FCGR3B (25% identical), FCRL6 (25% identical), FCGR2C (25% identical), FCGR3A (25% identical), FCER1A (22% identical), and 5 more.
Diseases named in the same sentence as FCGR1A in open-access papers:
FCGR1A is named in the same sentence as 205 diseases in open-access papers, as found by Europe PMC text mining. Sharing a sentence is not in itself a finding about the gene and the disease. The quoted sentences say what the papers report.
Sepsis (172 papers, 2008 to 2026). Sepsis is defined as life-threatening organ dysfunction caused by a dysregulated host response to infection. "In the sepsis group, FCGR1A and TLR5 were positively associated with survival compared to ELANE, IL1R2, RAB13, and RNASE3, which were adversely associated with survival." (PMID 39655195, 2024). "In the current study, elevated expression of FCGR1A in peripheral blood was associated with a good outcome in sepsis, and FCGR1A was mainly expressed in macrophages." (PMID 35332254, 2022). "Six core genes, ELANE, IL1R2, RAB13, RNASE3, FCGR1A, and TLR5, have been linked to sepsis prognosis." (PMID 39655195, 2024). "Meta-random-effects model analysis showed that elevated expression levels of ELANE, FCGR1A, IL1R2, and RNASE3 were associated with sepsis." (PMID 39655195, 2024). "As expected, the DCA results showed that BCL2A1 and FCGR1A yielded similar clinical values in the diagnosis of sepsis." (PMID 35832273, 2022). "The ROC curve analysis revealed that both BCL2A1 and FCGR1A had a high AUC for the diagnosis of sepsis in all three datasets." (PMID 35832273, 2022). "To further verify BCL2A1 as a novel diagnostic biomarker for patients with sepsis, we selected three other sepsis datasets (GSE28750, GSE69528, and GSE100159) to compare the diagnostic accuracy of BCL2A1 and FCGR1A in the disease." (PMID 35832273, 2022). "It was also revealed from our study that the level of FCGR1A was considerably elevated in sepsis, and this gene was also correlated to the prognosis of sepsis." (PMID 35832273, 2022). "The gene FCGR1A, which is also called CD64, is a classic sepsis-related biomarker which has been well studied and applied in the diagnosis of sepsis." (PMID 35832273, 2022). "Importantly, our findings indicate that high expression levels of ELANE, IL1R2, RAB13, and RNASE3 promote death rates in sepsis, whereas high expression levels of FCGR1A and TLR5 improve the survival rate of patients with sepsis." (PMID 39655195, 2024). "However, high expression of FCGR1A and TLR5 was associated with increased survival rates in the sepsis group compared to those in the control group." (PMID 39655195, 2024). "The gene FCGR1A, also called CD64, is a classic sepsis-related biomarker." (PMID 35832273, 2022). "Single-cell RNA sequencing analysis detected that FCGR1A and BCL2A1 might be potential biomarkers for sepsis diagnosis and the diagnostic efficacy of BCL2A1 was further validated by ROC curve and DCA." (PMID 35832273, 2022). "However, in terms of its suitability as a specific biomarker for Mycobacteriaceae-induced diseases, especially bovine paratuberculosis, FCGR1A is not suitable due to its characterization as a diagnostic biomarker of infection and sepsis in humans." (PMID 38668343, 2024). "Furthermore, the hub genes TLR5, FCGR1A, ELANE, GNLY, IL2RB and TGFBR3, which may be associated with the prognosis of sepsis, and their negatively correlated microRNAs, were analysed." (PMID 35332254, 2022). "ELANE, IL1R2, RAB13, and RNASE3 promote cell death, whereas FCGR1A and TLR5 facilitate cell survival in sepsis." (PMID 39655195, 2024). "In this study, we integrated bulk-RNA sequencing data and scRNA data and identified two biomarkers (FCGR1A and BCL2A1), which were closely related to sepsis and monocyte/macrophage." (PMID 35832273, 2022). "In the two groups of different expression trend modules, the core genes such as CD160, GATA2, GNLY, IL2RB and TGFBR3 were downregulated in the sepsis group, while genes such as ELANE, IL1R1, TLR5, FCGR1A, MAPK14 and PCSK9 were upregulated." (PMID 35332254, 2022). "The DEGs (IL1R2, ARG1, FCGR1A, MMP9, ELANE, and MPO) that were common on day1 and day3 of sepsis, with at least 2.0-fold upregulation, were selected for constructing and visualizing the PPI network using Cytoscape." (PMID 31817302, 2019).
Sepsis (continued). "In summary, these findings suggest that ELANE, IL1R2, RAB13, RNASE3, FCGR1A, and TLR5 may influence the prognosis of patients with sepsis and provide novel insights and potential avenues for the treatment of sepsis." (PMID 39655195, 2024). "Consequently, the genes TLR5, FCGR1A, ELANE, GNLY, IL2RB and TGFBR3 genes were ultimately identified as hub genes in sepsis." (PMID 35332254, 2022). "Finally, FCGR1A and BCL2A1 were found to be considerably increased in the sepsis group." (PMID 35832273, 2022). "The upregulation of FcγR‐related genes, such as FCGR3A, FCGR1A, LYN, SYK, FYN and SRC, was detected in the prefrontal cortex, hippocampus, heart and colon of our sepsis patients, but not in the kidneys or lungs." (PMID 37731199, 2023).
viral infection (28 papers, 2013 to 2025). "The gene encoding FcγRI (FCGR1A) showed elevated expression in MIS-C, bacterial infection and KD, in comparison with viral infection." (PMID 39300098, 2024).
COVID-19 (23 papers, 2021 to 2025). A disease caused by infection with severe acute respiratory syndrome coronavirus 2. "Additionally, CD16+ monocytes from people with COVID-19 compared to healthy donors have increased expression of genes such as FCGR1A and FCGR1B suggesting an increase in cell activation." (PMID 34108966, 2021). "Of the five proteins differentially expressed in cMs, four [transferrin receptor (TFRC), sialic acid binding Ig-like lectin 1 (SIGLEC1), Fc fragment of IgG receptor 1a (FCGR1A), and leukocyte-associated Ig-like receptor 1 (LAIR1)] were higher expressed in COVID-19+ cases." (PMID 34429372, 2021). "Since the FCgamma receptor signaling pathway is triggered by FCGR1A/2A/3A, we analyzed the expression of FCGR3A (CD16) in monocytes from our COVID-19 patient cohort." (PMID 37869162, 2023). "Meanwhile, CXCL8, S100A8, S100A9, S100A12, FCGR1A, PADI4, and BCL2A1 showed significant increases in severe COVID-19 when compared with mild COVID-19 (p <0.05)." (PMID 36159873, 2022).
tuberculosis (20 papers, 2011 to 2026). A chronic, recurrent infection caused by the bacterium Mycobacterium tuberculosis. "In the peripheral blood of human children with intrathoracic tuberculosis induced by Mtb, FCGR1A levels correlated with the extent of the disease." (PMID 38668343, 2024). "A study demonstrated that FCGR1A transcripts in peripheral blood could be used as a predictive marker of intrathoracic tuberculosis." (PMID 37273699, 2023). "Tuberculosis (TB) was the only disease with significant up-regulation of both VRGs and BRGs, albeit showing lower consistency in BRGs including much higher level of up-regulation of FCGR1A and FCGR1B compared to other BRGs." (PMID 28771541, 2017). "In another study, also in an Ethiopian cohort of HIV co-infected TB patients, 7 genes (FCGR1A, RAB24, TLR1, TLR4, MMP9, NLRC4, and IL1B) accurately discriminated between active tuberculosis disease and latent infection." (PMID 33692804, 2021). "Blood transcriptional profiling of ATB vs. LTBI revealed that interferon signaling genes (FCGR1A and FCGR1B) were predominantly upregulated during active tuberculosis as reported in earlier studies." (PMID 35456421, 2022). "The FCGR1A gene (Fc fragment of IgG receptor Ia) expression, together with that of the BLR1 gene has been considered as potential marker for monitoring the extent of TB disease and to predict treatment outcome in children affected by M. tuberculosis." (PMID 31480266, 2019). "Neutrophils FCGR1A is involved in tuberculosis (TB), regardless of HIV infection, and can be used to differentiate TB from latent TB infection." (PMID 35332254, 2022).
rheumatoid arthritis (15 papers, 2010 to 2026). A chronic, systemic autoimmune disorder characterized by inflammation in the synovial membranes and articular surfaces. "In the synovium of patients with rheumatoid arthritis, FCGR1A expression is upregulated and positively correlated with the expression of various matrix metalloproteinases, a trend consistent with changes observed in degenerated intervertebral discs." (PMID 40303407, 2025).
leukemia (10 papers, 2016 to 2025). A malignant (clonal) hematologic disorder, involving hematopoietic stem cells and characterized by the presence of primitive or atypical myeloid or lymphoid cells in the bone marrow and the blood. "Previous studies have reported that FCGR1A (CD64) is of great significance for diagnosis of leukemia." (PMID 33344503, 2020).
sarcoidosis (7 papers, 2017 to 2026). Sarcoidosis is a multisystemic disorder of unknown cause characterized by the formation of immune granulomas in involved organs. "FCGR1A gene variants were associated with the development and severity of sarcoidosis where granulomatous inflammation takes place in the pathogenesis of the disease." (PMID 39992598, 2025). "Our data suggest FCGR1A variant genotypes are risk factors for poor lung function in sarcoidosis patients, pointing to a role of FCGR1A in lung inflammation." (PMID 35371020, 2022). "FCGR1A SNV rs1050204 (p.D324N) genotypes were significantly associated with sarcoidosis susceptibility and poor lung functions." (PMID 35371020, 2022). "Genetic analyses revealed that FCGR1A genotypes were significantly associated with sarcoidosis susceptibility and severity." (PMID 35371020, 2022). "Subsequently, we carried out haplotype analysis to examine whether FCGR1A variant haplotypes are associated with the sarcoidosis susceptibility." (PMID 35371020, 2022). "Our data suggest that FCGR1A genetic variants may affect immune responses and play a role in sarcoidosis." (PMID 35371020, 2022). "Genetic analyses demonstrated that the FCGR1A SNV rs1050204 genotypes were associated with sarcoidosis susceptibility while the C-Del-A (rs1848781C-rs587598788Del-rs1050204A) haplotype was significantly associated with the protection against sarcoidosis." (PMID 35371020, 2022). "We subsequently carried out a genetic study to examine whether FCGR1A variants are associated with sarcoidosis susceptibility using the ACCESS cohort subjects." (PMID 35371020, 2022). "Our data suggest that functional FCGR1A variants may play important role in the pathogenesis of sarcoidosis." (PMID 35371020, 2022). "Our data suggest that FCGR1A genetic variants could affect immune responses and development of sarcoidosis." (PMID 35371020, 2022). "FCGR1A genetic variants affect CD64 expression and functions, which could play important roles in the development and manifestation of sarcoidosis." (PMID 35371020, 2022). "We analyzed whether FCGR1A variants are associated lung functions among sarcoidosis patients." (PMID 35371020, 2022). "Moreover, FCGR1A variants were associated with sarcoidosis susceptibility and disease severity." (PMID 35371020, 2022). "FCGR1A variants may serve as a biomarker for sarcoidosis susceptibility and severity." (PMID 35371020, 2022). "In sarcoidosis and common variable immune deficiency (CVID), moderate up-regulation of VRGs was observed, accompanied by the up-regulation of FCGR1A and FCGR1B in the BRG category." (PMID 28771541, 2017). "This suggests that FCGR1A could serve as therapeutic target to mitigate TNF mediated immune dysregulation in sarcoidosis." (PMID 36311769, 2022). "FCGR1A SNV rs1020204 genotypes were associated with sarcoidosis susceptibility (P = 0.042, PFDR = 0.111, OR 1.222, 95% CI 1.007 – 1.546) while rs587598788 genotypes tended to associate with sarcoidosis (P = 0.073, PFDR = 0.111, OR 1.431, 95% CI 0.962 – 2.128)." (PMID 35371020, 2022). "Taken together, our data suggest that FCGR1A haplotypes may affect the pathogenesis of sarcoidosis." (PMID 35371020, 2022).
cholangiocarcinoma (6 papers, 2020 to 2023). A carcinoma that arises from the intrahepatic biliary tree (intrahepatic cholangiocarcinoma) or from the junction, or adjacent to the junction, of the right and left hepatic ducts (hilar cholangiocarcinoma). "FCGR1A may be involved in the activation, regulation, or induction of immune cells and diverse physiological and pathological processes in endocervical cancer, cholangiocarcinoma, kidney renal clear cell carcinoma, and skin cutaneous melanoma." (PMID 35747790, 2022). "Three tumor antigens, such as CD247, FCGR1A, and TRRAP, correlated with superior prognoses and infiltration of antigen-presenting cells were identified in cholangiocarcinoma." (PMID 33685460, 2021). "CD247, FCGR1A, and TRRAP are potential antigens for mRNA vaccine development against cholangiocarcinoma, specifically for patients with IS2 tumors." (PMID 33685460, 2021). "FCGR1A was significantly correlated with the OS of cervical and endocervical cancer (CESC), cholangiocarcinoma (CHOL), kidney renal clear cell carcinoma (KIRC), and skin cutaneous melanoma (SKCM) (P < 0.05)." (PMID 33344503, 2020).
ovarian carcinoma (6 papers, 2023 to 2026). A malignant neoplasm originating from the surface ovarian epithelium. "In summary, this study verified that FCGR1A is associated with advanced-stage lymphatic metastasis and a poor prognosis in patients with ovarian cancer." (PMID 38879666, 2024). "The detection of FCGR1A is a potential marker for predicting occult abdominal metastases in recurrent ovarian cancer patients." (PMID 38879666, 2024). "FCGR1A promotes the metastasis of ovarian cancer cells The mechanism by which FCGR1A promotes abdominal metastasis in ovarian cancer patients is related to the regulation of EMT via LSP1." (PMID 38879666, 2024). "Our study is the first to identify FCGR1A as a promoter of metastasis in ovarian cancer through the regulation of LSP1 genes." (PMID 38879666, 2024). "The expression of FCGR1A and LSP1 in ovarian cancer cell lines was examined by quantitative real-time polymerase chain reaction (qRT‒PCR)." (PMID 38879666, 2024). "Siglec-9, the receptor of MUC16, had strong correlations with markers of neutrophil ITGAM, ITGB2, FCGR1A, FCGR2A, FCGR3A, analyzed with TCGA-OV database and ovarian cancer tissue RNA sequencing data." (PMID 37644468, 2023). "Notably, eight proteins upregulated in the invasive stroma (NNMT, FCGR1A, FCER1G, TYMP, F13A1, DCK, CASP3, and SYK) represented FDA-approved drug targets outside of ovarian cancer, emphasizing their high relevance for future preclinical investigations." (PMID 41233595, 2026).
breast carcinoma (5 papers, 2013 to 2024). "An in vitro study showed that the bispecific antibody MDX-447, which targets FCGR1A, mediated the efficient lysis of breast cancer cells, and the results from phase II and phase III clinical trials of MDX-447 in prostate and breast cancers have shown some efficacy." (PMID 38879666, 2024). "Based on the TCGA breast cancer microarray data alone, it is not clear if the detected expression of FCGR1A and FCGR2B is actually localised exclusively in the macrophages." (PMID 27876705, 2016).
leprosy (5 papers, 2016 to 2024). Leprosy is a chronic infectious disease affecting primarily the skin and peripheral nervous system. "These markers of innate immunity (CXCL10) and infection (FCGR1A) thus are increased in two different phases in leprosy associated either with M. leprae-specific T cell anergy and high bacterial load (BL/LL) or with a highly inflammatory state (RR)." (PMID 31784594, 2019). "When comparing leprosy patients to HHC, 16 genes showed significantly different expression for leprosy patients (increased: FCGR1A, IL6, IL15, LRKK2, MBP, MSR1, PACRGv1, TLR1, TLR4; decreased: CAMTA, CD3E, CTLA4, CXCL13, GATA3, LAG3, TFGB)." (PMID 31784594, 2019). "Additionally, we observed that a classification of leprosy patients is possible using transcriptomics since a set of genes were increased in BL/LL patients (CD46, CXCL10, FCGR1A, HDAC2 and TLR4) and TT/BT showed a higher expression of IL2 and TLR6." (PMID 31784594, 2019).
glioma (4 papers, 2020 to 2024). A benign or malignant brain and spinal cord tumor that arises from glial cells (astrocytes, oligodendrocytes, ependymal cells). "Additionally, FDA-approved drug targets among these genes revealed 30 such targets, with CDK4 and FCGR1A identified as glioma-specific and ADORA3 as brain-specific, according to the Human Protein Atlas." (PMID 39457550, 2024).
lung diseases (4 papers, 2013 to 2024). "The genes FCGR1A, B and C were over-abundant in the top 50 transcripts of all four pulmonary diseases." (PMID 23940611, 2013). "A recent study demonstrated that nine genes (CD274, CEACAM1, CR1, FCGR1A/B, IFITM1, IRAK3, LILRA6, MAPK14, and PDCD1LG2) showed 100% sensitivity and specificity that distinguished patients with active TB from those with other lung diseases (OPD)." (PMID 38674369, 2024).